NF1 (neurofibromin 1)
Diseases named in the same sentence as NF1 in open-access papers (continued):
Sharing a sentence is not in itself a finding about the gene and the disease.
melanoma (continued). "Recently, RASA2 and NRAS mutations were confirmed to be mutually exclusive, with NF1 mutations significantly co-occurring with RASA2 mutations in BRAF and NRAS wild-type melanomas, since RASA2 inhibits NRAS and NF1 inhibits KRAS and HRAS." (PMID 32850962, 2020). "In melanoma, ERK activation is most commonly due to the mutations of BRAF, followed by RAS, NF1, and other genes." (PMID 32083130, 2020). "All 37 were wild type for BRAF, NRAS, and NF1 genomic alterations (“triple wild-type”), representing 2.0% of triple wild-type melanomas overall (37/1882)." (PMID 32483240, 2020). "miR-514a overexpression in melanoma cell lines inhibits NF1 expression, which correlates with increased survival of BRAFV600E cells treated with Vemurafenib." (PMID 32054078, 2020). "Braf and Nf1, known melanoma driver genes, were found to be significantly downregulated in tumors treated with SAM+anti-PD-1 compared to control." (PMID 32983966, 2020). "Stark and coworkers demonstrated that miR-514a, which is expressed in 69% of melanoma cell lines, reverts drug resistance to BRAFi by directly binding to NF1 transcripts, leading to altered NF1 protein expression and consequent decreased cell proliferation." (PMID 32604720, 2020). "NF1 is a known driver of vemurafenib resistance in melanoma through its action as a negative regulator of RAS." (PMID 32346533, 2020). "In particular, miR-514a plays an important role in initiating melanocyte transformation and promoting melanoma growth by regulating the tumor suppressor NF1 gene." (PMID 32054078, 2020). "Malignant melanoma (MM) is the most life‐threatening disease among all skin malignancies, and recent genome‐wide studies reported BRAF, RAS, and NF1 as the most frequently mutated driver genes." (PMID 32406600, 2020). "NF1 mutations were reported to co-occur with mutations in the RASA2 gene that is another tumor suppressor gene inactivated in ca. 30% of melanomas and associated with poor prognosis." (PMID 32605090, 2020). "NF1 gene encodes for neurofibromin, a protein that negatively regulates the MAPK pathway: it is the third most commonly mutated gene in melanoma, found in 46% of cases with BRAF and NRAS wild type, and often co-mutated with RAS-associated genes." (PMID 33233603, 2020). "This novel mechanism for regulating NF1 in melanoma provides a molecular basis for targeting CAPN1 to suppress Ras activation." (PMID 32850962, 2020). "NF1 loss is considered a marker that confers resistance to targeted therapy not only in NF1-associated cancers like MPSNT, but also in sporadic cancers like lung carcinoma, melanoma, and neuroblastoma." (PMID 31906320, 2020). "Another miRNA involved in the regulation of melanoma response and resistance to vemurafenib is miR-514a that inhibits NF1 expression and thus confers vemurafenib resistance." (PMID 32555626, 2020). "In 82% of RAC1P29S/L cases analyzed there was a co-occurring mutation in one of the three main melanoma driver genes BRAF, NRAS, and NF1." (PMID 31257073, 2019). "Exposing transduced BRAFV600E A375 melanoma cells to the BRAF inhibitor vemurafenib yielded enrichment for known resistance gene NF1, as well as a handful of other genes including NF2." (PMID 31921397, 2019). "Based on the genomic DNA analysis, melanoma are categorized into four major subtypes that include BRAF-mutant, NRAS-mutant, NF1-deleted/mutated or triple negative melanoma." (PMID 31217906, 2019). "Four of the mutations in these genes, GRM3 p.D548N, GRM3 p.R668H, NF1 p.W336T, and NF1 p.P1851S, have been reported previously in COSMIC and/or TCGA studies of melanoma." (PMID 30312528, 2019).
melanoma (continued). "In contrast to lung adenocarcinoma and melanoma patients, the numbers of inactivating mutations in colorectal adenocarcinoma patients are low in all RASGAP genes (TCGA), including NF1." (PMID 30858928, 2019). "Previous studies have divided melanomas into four groups based on the driver mutation: BRAF-mutant, NRAS-mutant, NF1-mutant and triple-wild-type." (PMID 31322504, 2019). "The mutually exclusivity between loss-of-function mutations in NF1 and oncogenic mutations in RAS and BRAF is also observed in melanoma patients (TCGA)." (PMID 30858928, 2019). "In this study we applied SynGeNet, a computational drug combination prediction method, to four subtypes of melanoma based on genomic classification of major driver events, including mutations in BRAF, NRAS, NF1, and TWT tumors." (PMID 30820351, 2019). "Mutations in BRAF, particularly BRAF p.V600E, are the most commonly detected mutations in melanoma, followed by mutations in NRAS and NF1." (PMID 31684113, 2019). "This screening study tested drug combinations in each of the four genomic subtypes of melanoma, including one NF1-mutant melanoma cell line (MeWo) and one TWT melanoma cell line (COLO792)." (PMID 30820351, 2019). "Based on their somatic mutation profiles, melanomas can be divided into four genomic subtypes: BRAF, RAS (N/H/K), NF1, and triple wild‐type (WT)." (PMID 30312528, 2019). "Of the known melanoma driver mutations (BRAF, NRAS and NF1), only BRAF was mutated significantly more frequently in the better than in the poorer prognostic group (162/301 vs. 16/55; Fisher’s exact test, P = 0.001)." (PMID 31322504, 2019). "According to the TCGA data analysis, TERT promoter mutations frequently occur in melanoma, mainly in the BRAF (75% of cases), RAS (72% of cases), and NF1 (83% of cases) subtypes, suggesting a link between MAPK activation and TERT expression." (PMID 30166456, 2018). "Mass spectrometry was performed on endogenous NF1 co-immunoprecipitates that were generated from two melanoma cell lines: A375, a commercial melanoma cell line, and 74T, a cell line derived from a melanoma patient." (PMID 30131853, 2018). "This strong implication of NF1 in the drug resistance acquisition is reinforced by the evidence that NF1 mutations are coupled with drug resistance also in a human setting, in BRAF-mutant melanoma patients." (PMID 29534457, 2018). "Additionally, when we plotted the top 65 DEGs, we noticed that sample clustering was independent of mutations in the RAS (KRAS, NRAS, and HRAS) and NF1 genes, which have been described to modify gene expression patterns in melanoma, avoiding expression bias that might be caused by those genes." (PMID 30242167, 2018). "NF1 loss has been shown to drive resistance to RAF inhibitor, dasatinib, tamoxifen and retinoic acid in melanoma, lung cancer, breast cancer and neuroblastoma, respectively." (PMID 30131853, 2018). "BRAFV600E is the most prevalent mutation in melanoma, being detected in 52% of cases, followed by mutations in the RAS family and neurofibromin 1 (NF1) in approximately 30 and 14% of cases, respectively." (PMID 30166456, 2018). "Metastatic melanomas are subdivided by their mutation profile into four subtypes BRAF driven (about 52%), NRAS driven (28%), Neurofibromin 1 (NF1) mutated (14%) and in “triple wild type”." (PMID 30360441, 2018). "As a supplementary observation, the occurrence of a case of melanoma in our limited cohort seems to support the role NF1 and neurofibromin in neural crest-derived neoplasms, such as melanoma and other tumors." (PMID 30271432, 2018).
melanoma (continued). "Immunoblotting confirmed the specific targeting of CAPN1 by shRNAs, NF1 stabilization, as well as a reduction in pAKT-308 and pAKT-473 in both melanoma cell lines, while ERK activation remained unchanged." (PMID 30131853, 2018). "Specific mutations have now been correlated with high TMB, including NF1 mutations in melanoma and PMS2 mutations in melanoma and squamous cell carcinoma." (PMID 29725606, 2018). "We split the candidate features into four groups: (i) clinical variables (i.e., gender, age, pretreatment, and pathologic stage); (ii) mutation status of three well-known melanoma driver genes (BRAF, NRAS, and NF1); (iii) mutation load; and (iv) ECPAcell." (PMID 30297703, 2018). "Loss of NF1 has been reported to result in resistance to various targeted tyrosine kinase inhibitors in a number of settings, including BRAF-mutant melanoma and EGFR-mutant lung cancer." (PMID 29435137, 2018). "In melanoma, CRISPR screens have looked for genes whose loss confers resistance to the BRAF inhibitor vemurafenib, identifying targets such as NF1, whose loss results in activation of NRAS, a recognized vemurafenib resistance mechanism." (PMID 28097822, 2017). "Similar results were obtained in NF1 null melanoma cell line, MeWo, indicating a strong correlation between NF1 status and glutamine dependency." (PMID 29212209, 2017). "The majority of melanomas have an activated MAPK pathway, and recently, melanoma tumors were stratified into genomic subtypes according to mutations in the BRAF, RAS, or NF1 genes." (PMID 28267273, 2017). "The re-analysis enabled us to solve one case with an uncertain clinical diagnosis: a whole CDKN2A deletion causing melanoma and neural system tumor syndrome (OMIM: 155755) was identified in the patient with clinical suspicion of NF1 (Sample R2)." (PMID 28051113, 2017). "A recent study based on 213 human melanoma samples identified three frequently mutated genes: BRAF, NRAS and NF1, with frequencies of 38.5, 28.6 and 12.2%, respectively." (PMID 28637487, 2017). "An RNAi screen, targeting more than 16,500 genes in a BRAF inhibitor-sensitive melanoma cell line, identified NF1 as the highest ranking protein affected by BRAF inhibition, and that, NF1 knockdown abrogated the growth inhibitory effects of BRAF inhibition." (PMID 28637487, 2017). "NF1 is strongly affected by the treatment of BRAF-sensitive melanoma cell lines with BRAF inhibitors, and NF1 knockdown abrogated the growth inhibitory effects elicited by BRAF inhibition." (PMID 29156643, 2017). "Similar selectivity and efficacy of trametinib was also reported as a single-agent in wild-type BRAF/NRAS, NF1-altered melanomas." (PMID 29156677, 2017). "The most frequent mutations were identified in the NF1 gene and RAS gene family members, indicating that mucosal melanomas have a genetic mutation profile which is different from that of cutaneous or uveal melanomas." (PMID 28380455, 2017). "In this study, we found that the EPE peptide significantly reduced the viability of not only BRAF, but also several NRAS and NF1 mutant melanomas." (PMID 29180761, 2017). "Clinical and pathological properties partly reflect the identified (BRAF, RAS, NF1, triple wild type) genomic subtypes of melanoma, but from both clinical and genetic perspective the groups still are heterogeneous." (PMID 28445515, 2017). "In a mouse melanoma model, NF1 mutations cooperate with BRAF mutations in the pathogenesis of melanoma by preventing oncogene-induced senescence, an indication that NF1 plays a key role in early melanoma development." (PMID 28637487, 2017). "As neurofibromin activity is a key to regulating the RAS/MAPK pathway, NF1 mutations are important in the acquisition of drug resistance, to BRAF, EGFR inhibitors, tamoxifen and retinoic acid in melanoma, lung and breast cancers and neuroblastoma." (PMID 28637487, 2017).
melanoma (continued). "For melanoma cell lines, the preeminent factors are the presence of the most significantly mutated genes (BRAF, NRAS, NF1, or triple wild type) and proliferative or invasive behavior (MITF/AXL expression ratio)." (PMID 29383127, 2017). "In both mouse tumour models and A375 human melanoma cell lines, Maertens and colleagues have shown that resistance to treatment was enhanced by further suppression of NF1 by small hairpin RNA (shRNA)." (PMID 28637487, 2017). "In melanoma, the MAPK pathway can also be activated as a result of mutations in BRAF genes (e.g., BRAFV600E) or loss of neurofibromatosis type 1 (NF1) activity due to inactivating mutations." (PMID 27608486, 2016). "We found that NRAS-mutant melanoma cells were significantly more resistant to the cytotoxic effects of DNA replication stress-inducing drugs compared to other genotypes (BRAF-mutant, NF1-deficient, or triple wild-type)." (PMID 27608486, 2016). "Common genes associated with aggressive melanoma include BRAF, with these mutations comprising the majority of melanoma cases (37–50%), followed by NRAS (13–25%) and NF1 (11.9%)." (PMID 27829238, 2016). "The selected cell line's mutations represented melanoma - eight CDX samples originated from BRAF mutant melanoma, SK-MEL-2 harbored an activating Q61R NRAS mutation and MeWo carried multiple NF1 inactivating mutations." (PMID 27009863, 2016). "Surprisingly, we also found that NRAS-mutant melanoma cells were significantly more resistant to the drugs that induce DNA replication stress than were BRAF-mutant, NF1-deficient, or triple wild-type melanomas." (PMID 27608486, 2016). "Four of the melanomas had BRAFV600E mutations, three had NRAS mutations, three had NF1 mutations and one had a MAP2K1 (MEK1) mutation." (PMID 27545456, 2016). "The majority of melanomas carry mitogen-activated protein kinase (MAPK) pathway-activating mutations, especially in BRAF, NRAS, NF1; providing avenues for targeted therapeutic intervention." (PMID 27009863, 2016). "For example, up-regulated miR-514 not only regulates the expression of NF1, a well-known tumor-suppressor gene in melanoma, but also contributes to altered BRAFi sensitivity in vitro." (PMID 27448964, 2016). "Our observation is consistent with a recent report that loss of a RasGAP, Nf1, cooperates with BRAF activation in melanoma tumorigenesis in a genetically engineered mouse model." (PMID 26993606, 2016). "Luciferase-reporter assays confirmed NF1 as a direct target of miR-514a and over-expression of miR-514a in melanoma cell lines inhibited NF1 expression, which correlated with increased survival of BRAFV600E cells treated with PLX4032." (PMID 25980496, 2015). "In a mouse model, NF1 ablation decreases the sensitivity of NF1 wild-type melanoma cell lines to BRAF inhibitors, and NF1 is lost in tumors from patients following treatment with these agents." (PMID 24743024, 2014). "Somatic NF1 aberrations are increasingly reported in various sporadic tumours, including brain, lung, breast, ovarian tumours as well melanomas and leukemias." (PMID 25026295, 2014). "More recently, somatic NF1 aberrations have been increasingly reported in various sporadic tumours, including brain, lung, breast, ovarian tumours and melanomas." (PMID 25026295, 2014). "The search for driver mutations in melanoma continues, with the previously identified subtypes involving BRAF, NRAS, KIT, GNAQ, and GNA11 expanded recently to include NF1 and telomerase." (PMID 24743024, 2014). "A pooled RNA interference screen targeting >16,500 genes in a BRAF inhibitor-sensitive melanoma cell line identified NF1 as the highest ranking gene whose knockdown abrogated the growth inhibitory effects of PLX4720, a BRAF inhibitor." (PMID 25026295, 2014). "NF-1 was recently identified as top hit in an shRNA screen designed to identify genes whose disruption convey BRAF inhibitor resistance in melanomas." (PMID 24970815, 2014).
melanoma (continued). "LOH in tumor suppressor inhibitor of growth 1 (ING1) is associated with carcinogenesis in human non-small cell lung cancer, and deletion in the neurofibromin 1 (NF1) gene promotes formation of malignant melanoma." (PMID 25493073, 2014). "The inactivation pattern of the NF1 gene in the analyzed melanoma represents the classical double-hit inactivation of a tumor suppressor gene as postulated by Knudson in 1971." (PMID 16961930, 2006). "We hereby want to report the first molecular evidence of inactivation of both copies of the NF1 gene in a typical superficial spreading melanoma of a 15-year-old boy with NF1." (PMID 16961930, 2006). "Of the NF1 group, 24% had developed malignant tumours (16% carcinoma, 7% sarcoma, 1% melanoma) and 17% had developed benign tumours (7% GIST, 6% pheochromocytoma, 3% adenoma and 1% meningioma)." (PMID 16640782, 2006). "In Europe, melanoma incidence lies around 10/100,000/year and melanoma has been found in 0.1–5.4% of NF1 patients." (PMID 16961930, 2006). "The classical double-hit inactivation of the NF1 gene suggests that the NF1 genetic background promoted melanoma genesis in this patient." (PMID 16961930, 2006). "Again, more cases need to be studied to exclude the possibility that LOH for NF-1 occuring as a late event in the tumorigenesis of sporadic melanomas." (PMID 15363097, 2004). "This presumption contradicts the notion that in patients with NF-1, malignant melanomas that rarely develop are part of their neurocristopathy." (PMID 15363097, 2004). "In a follow-up study of 70 NF-1 patients reported to the Swedish Cancer registry, 24% of the 70 patients developed 19 malignancies, only 1 of which was a melanoma." (PMID 15363097, 2004). "This review explores the molecular mechanisms regulating signaling pathways that may be potentially involved in modulating apoptosis in melanoma tumor cells harboring mutations in BRAF, NRAS, and NF1 genes." (PMID 42193039, 2026). "Nf1 haploinsufficiency accelerated melanoma formation and/or growth." (PMID 39804140, 2025). "Shain and colleagues reported that 54% of desmoplastic melanomas are NF1 mutant." (PMID 39804140, 2025). "Also, Spitz melanomas are thought to generally have a more favourable prognosis than melanomas with BRAF, NRAS, or NF1 mutations." (PMID 40107205, 2025). "In addition, Pten or Nf1 loss abrogates BrafV600E‐induced oncogene‐induced senescence (OIS) and leads to in vivo melanoma formation and Lkb1 loss abrogates BrafV600E‐induced cell growth arrest without full progression to malignancy." (PMID 39115053, 2025). "There was only one DE gene that was found in both melanoma tumor types when Nf1 was mutant." (PMID 39804140, 2025). "In addition to UVR, the expression of BRAFV600E combined with the silencing of the tumor suppressor PTEN or the downregulation of the tumor suppressor NF1 induces melanoma development and progression." (PMID 39115053, 2025). "Further, a subset of individuals with NF1 wild-type MPNST (3-12% depending on the study) have been reported to harbor BRAF mutations, among which BRAFV600E is the most frequent, similar to observations in melanoma and additional epithelial cancers." (PMID 41063628, 2025). "Notably, mucosal melanoma exhibits distinct molecular characteristics compared to its cutaneous counterpart, such as a lower BRAF mutation rate and a higher prevalence of NF1 mutations, which restrict the applicability of targeted therapies." (PMID 40969261, 2025). "However, we did not specifically assess the performance of the KMPAG signature within distinct molecular or etiological subtypes (e.g., NF1-mutant melanomas, which can exhibit RAS pathway activation, or acral vs. mucosal melanomas)." (PMID 40607411, 2025).